SERPINE2 (serpin family E member 2)
Diseases named in the same sentence as SERPINE2 in open-access papers (continued):
Sharing a sentence is not in itself a finding about the gene and the disease.
colorectal cancer (continued). "Bioinformatics analysis was used for exploring the mRNA expression level of SERPINE family in Pan-cancer, the prognostic significance of SERPINE family overexpression in four cancer types, the clinical relevance of SERPINE2 and the potential function of SERPINE2 in colorectal cancer." (PMID 40463876, 2025). "However, we aimed to validate the overexpression of SERPINE2 in colorectal cancer and explore its correlation with macrophages." (PMID 40463876, 2025). "Furthermore, we analyzed SERPINEs at the mRNA and protein level in colorectal cancer and clinical relevance of SERPINE2 in Colorectal Cancer Patients." (PMID 40463876, 2025). "Moreover, targeting of serpinE2 by mRNAi in human colorectal cancer cell lines decreased anchorage independent growth, migration, invasion as well as tumor formation in nude mice." (PMID 20942929, 2010). "Two human CRC cell lines, namely HCT116 and LoVo, which have an activating mutation in the KRAS gene resulting in elevated MEK/ERK activities, were thereby chosen to further analyze the regulation and role of serpinE2 expression in human colorectal cancer cells." (PMID 20942929, 2010). "Accordingly, we observed herein that the downregulation of serpinE2 significantly delayed colorectal carcinoma cell detachment after trypsinization, suggesting that serpinE2 expression does decrease adhesion and promote detachment of colorectal carcinoma cells." (PMID 20942929, 2010). "Therefore, it is speculated that SERPINE2 may serve as an important secretory factor promoting the malignant progression of colorectal cancer." (PMID 40463876, 2025). "SERPINE2 might be a vital gene for intestinal health and disease, such as colorectal cancer." (PMID 35928108, 2022). "We selected normal intestinal cell line NCM460 and colorectal cancer cell lines, including HCT-8, HCT-15 to validate the expression of SERPINE2." (PMID 40463876, 2025). "Therefore, SERPINE2 may be a potential therapeutic target for colorectal cancer treatment." (PMID 33317533, 2020). "SERPINE2 can enhance the tumor-promoting effect of ERK signal transduction in intestinal epithelial cells and is a potential therapeutic target for colorectal cancer." (PMID 32843852, 2020). "Hence, serpinE2 may be a potential therapeutic target for colorectal cancer treatment." (PMID 20942929, 2010). "Our results also led to the demonstration that serpinE2 contributes to transformation induced by activated MEK1 and to human colorectal carcinoma cell growth and migration." (PMID 20942929, 2010). "However, the biological roles of serpinE2 in colorectal carcinoma have never been studied." (PMID 20942929, 2010).
lung carcinoma (10 papers, 2010 to 2025). "Metastasis of lung cancer cells towards bone is also associated with increased SERPINE2 expression." (PMID 23213280, 2012). "The overexpression of Serpine2 in CAF-derived exosomes was found to further augment the malignant phenotype of lung cancer cells." (PMID 40642075, 2025). "Previous studies reported that SERPINE2 can regulate the DNA damage response induced by IR in lung cancer and that knocking down SERPINE2 leads to abnormal DNA damage repair, resulting in radiation-induced cell death." (PMID 39273235, 2024). "Recent investigations have revealed a correlation between elevated SERPINE2 expression and reduced overall survival in patients, signifying its potential as a prognostic biomarker for lung cancer." (PMID 38383657, 2024). "Upregulation of SERPINE2 has been reported to increase the radioresistance of lung cancer cells and is also involved in the invasion and metastasis of endometrial cancer." (PMID 37691944, 2023). "Consistent with the transcriptome data, SERPINE2 was more highly expressed in lung cancer tissues compared with that in paratumor tissues, while a low expression of FGF10, LSAMP, and PDE5A was found in lung cancer tissue." (PMID 37280069, 2023). "They revealed that the expression of Serpine2 in exosomes secreted by CAFs was significantly elevated compared to those secreted by normal fibroblasts, thereby enhancing the malignant phenotype of lung cancer cells." (PMID 40642075, 2025). "The results of the current experiment suggest that SERPINE2 suppresses apoptosis in lung cancer cell lines and may be a target molecule for lung cancer treatment." (PMID 33317533, 2020). "However, serpinE1 (or plasminogen activator inhibitor-1, PAI-1) has been reported to promote angiogenesis and to induce tumor cell migration while serpinE2 (or protease nexin-1, PN-1) appears to enhance the invasive potential of pancreatic, breast and lung cancer cells." (PMID 20942929, 2010). "Cell number assays and cell apoptosis assays were performed to clarify the cell-autonomous function of SERPINE2 in A549 and PC9 lung cancer cells." (PMID 33317533, 2020). "Among lung cancer cell lines, H460, A549 and PC9 more highly express SERPINE2 compared to BEAS-2B, which is a bronchial epithelial cell line." (PMID 33317533, 2020). "Furthermore, BMP4, which plays a crucial role in migration and invasion, was not activated by SERPINE2 knockdown in A549 and PC9 lung cancer cells." (PMID 33317533, 2020).
pancreatic cancer (10 papers, 2011 to 2025). "In pancreatic cancer, SERPINE2 overexpression has been associated with significantly increased local invasiveness, accompanied by a substantial increase in ECM production." (PMID 39492622, 2024). "For example, a highly differentially expressed protein, SERPINE2, has been linked to invasiveness in pancreatic cancer." (PMID 30651077, 2019). "In pancreatic cancer, SERPINE2 promotes pancreatic cancer invasion by promoting extracellular matrix deposition." (PMID 36505099, 2022). "PSC can also enhance the invasion-promoting effect of SERPINE2, which is secreted by pancreatic tumor cells." (PMID 24213498, 2012). "In pancreatic tumors, on the other hand, SERPINE2 promotes extracellular matrix production and local invasion in vivo." (PMID 23213280, 2012). "As a biomarker of immunosuppression and fibrosis, SERPINE2 could serve as a poor prognostic factor for pancreatic cancer." (PMID 37280069, 2023). "Blocking the SERPINE2-related signaling pathway could overcome the resistance of chemo- or immunotherapy against pancreatic cancer." (PMID 37280069, 2023). "Moreover, SERPINE2 does not affect tumor growth in the absence of PSC, but augments proliferation of pancreatic cancer cells and thus tumor growth only in the presence of PSC." (PMID 24213498, 2012).
hepatocellular carcinoma (9 papers, 2020 to 2025). A malignant tumor that arises from hepatocytes. "In hepatocellular cancer, BAP31 enhancing cell proliferation is found to be associated with serpin family E member 2 (SERPINE2) stabilization, and administration of anti-BAP31 antibody could significantly prevent in vivo tumor growth." (PMID 35359416, 2022). "In addition, reducing YTHDF2 reduced m6A-containing IL11 and SERPINE2 mRNA in hepatocellular carcinoma to aggravate inflammation and vascular abnormalities." (PMID 33505426, 2020). "In our previous study, using mIHC and multispectral imaging techniques, we demonstrated that BAP31 promotes cell proliferation by interacting with Serpin Family E Member 2 (SERPINE2) in hepatocellular carcinoma (HCC)." (PMID 39834395, 2024). "In hepatocellular carcinoma, BAP31 promotes tumor proliferation via protein interaction with SERPINE2." (PMID 37296105, 2023). "YTHDF2 silencing provoked tumor-promoting inflammation, vascular reconstruction, and energy metabolism reprogramming in hepatocellular carcinoma by inhibiting the degradation of m6A-modified IL11 (interleukin 11) and SERPINE2 (serpin family E member 2) transcripts." (PMID 37028765, 2023). "In addition, YTHDF2 inhibits the normalization of tumor vasculature in hepatocellular carcinoma cells by increasing the attenuation of IL11 and SERPINE2 mRNAs." (PMID 35572524, 2022).
prostate carcinoma (9 papers, 2012 to 2025). A carcinoma that arises from epithelial cells of the prostate gland. "On the other hand, it was reported in a study using prostate cancer cells that apoptosis was induced by SERPINE2, and it is believed that the effect differs depending on the cancer type." (PMID 33317533, 2020). "It has been shown in a prostate cancer model that high serpinE2 expression inhibits tumor cell invasion and metastasis, via its ability to negatively regulate the Hedgehog (Hh) pathway." (PMID 27793045, 2016). "Indeed, overexpression of SERPINE2 in prostate cancer cells reduces their invasion capacity, and in experimental OS, inhibition of uPAR pathway resulted in decreased lung metastasis." (PMID 23213280, 2012). "At first sight, the role of Serpine2/PN-1 appears at odds with its established role in inhibiting SHH signaling and GNP proliferation during cerebellar development and its recently demonstrated functions in reducing proliferation of metastatic prostate cancer cells." (PMID 25901736, 2015).
chronic obstructive pulmonary disease (8 papers, 2007 to 2022). A chronic and progressive lung disorder characterized by the loss of elasticity of the bronchial tree and the air sacs, destruction of the air sacs wall, thickening of the bronchial wall, and mucous accumulation in the bronchial tree. "The association between SERPINE2 gene polymorphisms and chronic obstructive pulmonary disease was confirmed in a subsequent study." (PMID 35592395, 2022). "The SERPINE2 gene was identified as a candidate susceptibility gene for chronic obstructive pulmonary disease." (PMID 35592395, 2022). "SERPINE2 is a serine protease inhibitor and is a known susceptibility gene for chronic obstructive pulmonary disease, emphysema and asthma." (PMID 30206357, 2019). "SERPINE2 (serpin peptidase inhibitor, clade E, member 2) has previously been identified as a positional candidate gene for chronic obstructive pulmonary disease (COPD) and has subsequently been associated to COPD and emphysema in several populations." (PMID 22145704, 2011). "Recent studies have proposed that the serine protease inhibitor E2 (SERPINE2) was a novel susceptibility gene for chronic obstructive pulmonary disease (COPD) in Caucasians." (PMID 19604412, 2009). "Subsequently, the gene of another member of the serpin-family, SERPINE2, has been associated to chronic obstructive pulmonary disease (COPD) and emphysema in several populations." (PMID 23734748, 2013). "The SERPINA1, SERPINA3, and SERPINE2 genes, which encode antiproteases, have been proposed to be susceptible genes for of chronic obstructive pulmonary disease (COPD) and related phenotypes." (PMID 21067581, 2010).
gastric cancer (8 papers, 2019 to 2022). A primary or metastatic malignant neoplasm involving the stomach. "SERPINE2 is overexpressed in gastric cancer and is associated with poor survival, promoting gastric cancer cell migration and invasion." (PMID 36505099, 2022). "The study aimed to identify the role of hsa_circ_0008365 (Circ‐SERPINE2) in gastric carcinoma (GC) cells and its downstream mechanisms." (PMID 31199037, 2019). "Moreover, the correlation analysis of clinicopathological characteristics of gastric carcinoma patients and the expression of circ‐SERPINE2 indicated high expression of circ‐SERPINE2 was related to poor TNM stage (P < 0.05)." (PMID 31199037, 2019). "Sponging functions of circular RNAs, circ-SERPINE2 and YWHAZ, have been reported in a recent study to influencing miR-375 function in gastric cancer." (PMID 34660323, 2021). "In gastric cancer, circ-SERPINE2 sponges miR-375 and regulates YWHAZ (tyrosine 3-monooxygenase/tryptophan 5-monooxygenase activation protein zeta) expression to promote the development of gastric cancer." (PMID 35440286, 2022). "In human gastric cancer cells (AZ521, MGC-803), circ-SERPINE2 could competitively bind to miR-375 to affect the transcription of YWHAZ, thereby promoting the development of gastric cancer." (PMID 34494089, 2021). "The mechanism for miR-488-3p down-regulation are complex, recent studies have provided new biological explanation for the regulation of miRNAs, in which demonstrated circ‐SERPINE2 can promote cell proliferation by sponging miR‐375 and regulating YWHAZ expression in gastric carcinoma cells." (PMID 32231744, 2020).
glioma (8 papers, 2012 to 2022). A benign or malignant brain and spinal cord tumor that arises from glial cells (astrocytes, oligodendrocytes, ependymal cells). "SERPINE2 is a protein that is secreted into the extracellular matrix, and it inhibits cell invasion in PCa and glioma, which is related to the inhibition of uPA, MMP-2, and MMP-9 activities." (PMID 36142828, 2022). "Serine proteinase inhibitor clade E member 2 (SERPINE2), also known as protease nexin-1 (PN-1), was first identified as a neurite-promoting factor released by cultured glioma cells." (PMID 33317533, 2020). "SERPINE2 expression is regulated by pro-inflammatory cytokines and in the last years, it was suggested a role for SERPINE2 in the regulation of matrix metalloproteinases activity in glioma and endothelial cells, and in the muscle ECM homeostasis." (PMID 26305372, 2015). "Serpine2 was identified as an oncogenic agent in GSCs, which could be transported to glioma cells to enhance their tumorigenicity by regulating the miR-124-3p/KIF20A axis." (PMID 36321132, 2022). "Serpine2 was found to be upregulated in GSCs and could be delivered to glioma cells inside exosomes, to enhance glioma cell tumorigenesis." (PMID 36321132, 2022). "In addition to glioma cells, various other cells secrete SERPINE2, including endothelial cells, fibroblasts, macrophages, platelets, smooth muscle cells, chondrocytes, astrocytes, and several types of tumor cells." (PMID 33317533, 2020). "Accordingly, very recently was demonstrated that SERPINE2 gene knockdown increased MMP-9 and MMP-2 expression in C6 glioma cell line." (PMID 26305372, 2015). "Through circRNA sequencing and differential analysis, we found that hsa_circ_001588 (Serpine2) was highly upregulated in GSC23 compared to glioma cells, miR-124-3p was severely downregulated in glioma cells, and KIF20A was significantly upregulated in gliomas." (PMID 34689806, 2021). "Our study shows that high motility gliomas expressing Cx43 differ from their parental counterparts by the upregulation of MMP3, osteopontin, aldo-keto reductase family 1 member B10 (ARK1B10), and to a lesser degree SERPINE2 (2.5-fold, P = 0.03), and phosphoglycerate kinase 1 (2.4-fold, P = 0.04)." (PMID 30941001, 2019).
asthma (7 papers, 2016 to 2022). "Gene-based analyses identified NRP2, MRPL44 and SERPINE2 to be associated with various asthma and allergy-related traits." (PMID 30206357, 2019). "However, our results are in agreement with those from an association study between different SERPINE2 SNPs and asthma-related phenotypes, including lung function, which weakly support this hypothesis." (PMID 26986948, 2016). "For females, gene SERPINE2 in one of the identified DMRs has been connected with asthma based on genetic studies." (PMID 35207690, 2022). "Other genes associated with 3 or fewer gene sets have also been associated with asthma such as Plasminogen Activator, Urokinase Receptor (PLAUR) and Serpin Family E Member 2 (SERPINE2), and several additional genes were first identified here." (PMID 28886691, 2017). "SERPINE2 has a known link to airway obstruction, with strong evidence of association with COPD and some evidence of association with childhood asthma." (PMID 26836265, 2016). "SERPINE2 is associated with lung function in COPD patients, and it has been hypothesized that it is a common genetic determinant of asthma and COPD (i.e. the Dutch hypothesis)." (PMID 26986948, 2016). "Eight protein-disease pairs were ranked as the most valuable findings after the filtering, which include IL-7R and TNFSF12 level on asthma; ACE level on COPD; AIF1 level on HF; SERPINF1 level on stroke; and SERPINE2, F11, KLKB1, and ABO level on VTE." (PMID 36388766, 2022).
endometrial cancer (6 papers, 2020 to 2023). Primary or metastatic malignant neoplasm involving the endometrium (mucous membrane that lines the endometrial cavity). "Serine protease inhibitor E2 (SerpinE2), a poor prognostic biomarker of endometrial cancer (EC), promotes the proliferation and mobility of EC cells." (PMID 35300639, 2022). "Silencing SERPINE2 can induce apoptosis in endometrial cancer cells." (PMID 36505099, 2022). "Moreover, SERPINE2 contributes to enhanced invasion, metastasis, and stemness of cancer cells by remodeling the tumor matrix, and has been identified as a poor biomarker for endometrial cancer." (PMID 32850407, 2020).
esophageal squamous cell carcinoma (6 papers, 2020 to 2025). Esophageal squamous cell carcinoma (ESCC) is a type of esophageal carcinoma (EC) that can affect any part of the esophagus, but is usually located in the upper or middle third. "SERPINE2 is closely associated with the depth of invasion and lymph node metastasis of esophageal squamous cell carcinoma and promotes the migration and invasion of esophageal carcinoma cells by inducing EMT." (PMID 36505099, 2022). "In esophageal squamous cell carcinomas, SERPINE2 inhibition resulted in a reduction in cell growth, migration and invasion." (PMID 33317533, 2020). "In esophageal squamous cell carcinomas, SERPINE2 promotes tumor metastasis by activating bone morphogenetic protein 4 (BMP4)." (PMID 33317533, 2020).
testicular cancer (6 papers, 2010 to 2021). A primary or metastatic malignant neoplasm that affects the testis. "SERPINE2 is overexpressed in a large number of invasive/metastatic tumors including breast, prostate, pancreatic, colorectal, oral-squamous, and testicular cancers and is required for tumor growth and malignant progression." (PMID 28255192, 2017). "In particular, Serpine2/PN-1 is up-regulated in a large number of invasive/metastatic tumors including breast, prostate, pancreatic, colorectal, oral-squamous, and testicular cancers and is required for tumor growth and malignant progression." (PMID 25901736, 2015). "SERPINE2, shown to be upregulated in hemangioma derived endothelial cells and mediating lymph node metastasis in testicular cancer, was downregulated in the podoplaninhigh population most likely by an interaction with miR-513a-3p, miR-186 and miR-559." (PMID 25502694, 2014). "Finally, serpinE2 has recently been shown to promote lymph node metastasis in a testicular cancer model." (PMID 20942929, 2010).
breast tumor (5 papers, 2010 to 2024). "We have previously shown that serpinE2 knock-down (KD) in an aggressive breast tumor model blocked metastasis." (PMID 27793045, 2016). "In agreement with the present study, data on serpinE2 expression in human cancer indicate that serpinE2 levels are elevated in pancreatic tumors, breast tumors, liposarcomas and oral squamous carcinomas." (PMID 20942929, 2010). "Furthermore, serpinE1 is overexpressed in highly aggressive human breast tumors while serpinE2 levels are elevated in pancreatic tumors, breast tumors, oral squamous carcinomas, liposarcomas and more recently CRCs." (PMID 20942929, 2010). "The mouse model of breast tumor heterogeneity demonstrated that SERPINE2 provokes tumor cells to form vascular networks that mimic blood vessels to facilitate tumor cells penetration and metastasis, indicating that SERPINE2 is a dominant driver of metastatic progression." (PMID 36011368, 2022). "We previously showed that high serpinE2 levels were preferentially found in more malignant grade 3 breast tumors, and in estrogen receptor (ER) negative tumors." (PMID 27793045, 2016).